KDM6A (lysine demethylase 6A)
Diseases named in the same sentence as KDM6A in open-access papers (continued):
Sharing a sentence is not in itself a finding about the gene and the disease.
tumor (continued). "Strikingly, we observed decrease of Deptor expression and accompanied increase in S6RP phosphorylation on CRISPR/Cas9 mediated knockout of Kdm6a in isogenic murine cancer cell lines derived from Myc;sgTp53 and Myc;sgAxin1 tumours." (PMID 34509979, 2022). "KDM6A is an important tumour suppressor in gastrointestinal cancers and acts as an epigenetic toggle for mTORC1 signalling." (PMID 34509979, 2022). "To confirm the role of KDM6A in tumour metastasis in vivo, we performed tail vein xenografts in BALB/c (nu/nu) mice." (PMID 34006303, 2021). "Boxplot analysis between tumor and normal tissues showed a lower KDM6A expression, lower KDM6A exon expression, and higher KDM6A DNA methylation in COAD (p < 0.0001, p = 0.0009, p = 0.0014), and READ (p = 0.0017, p = 0.0203, p = 0.4499)." (PMID 33174323, 2021). "Although KDM6A plays an important role in tumour progression, the regulatory mechanism of KDM6A is poorly understood." (PMID 34006303, 2021). "The underlying mechanisms and affected pathways have to be investigated in future research to understand how tumor cells cope with and benefit from KDM6A truncations." (PMID 34702163, 2021). "KDM6A showed lower expression in tumor tissues than in normal tissues in COAD, and pMMR was a poor prognostic marker in COAD." (PMID 33174323, 2021). "An exciting finding is that loss of KDM6A in a UBC xenograft model predisposed tumor cells to epigenetic therapy, which diminished in vivo tumor growth and increased natural killer cell attack." (PMID 34768683, 2021). "Tumour xenograft models were employed to further evaluate the effect of the KDM6A on tumour growth in vivo." (PMID 34006303, 2021). "Despite the important roles of KDM6A in the tumorigenesis of BCa, its functions and detailed mechanisms in tumour progression and metastasis are poorly understood." (PMID 34006303, 2021). "In human T-ALL, KDM6A acts as a tumor suppressor and is frequently genetically inactivated in a NOTCH1-induced T-ALL model." (PMID 34950587, 2021). "For instance, KDM6A is a tumour suppressor in T-cell acute lymphoblastic leukaemia (T-ALL), except in T-ALL driven by TAL bHLH transcription factor 1 (TAL1)." (PMID 34006303, 2021). "This study can help to elucidate the effect of KDM6A on the tumour microenvironment and develop a potential immunotherapy strategy for BC patients." (PMID 34051747, 2021). "Accordingly, IHC staining showed dramatically increased Ki-67 expression in the KDM6A knockdown tumours but decreased Ki-67 expression in the overexpressed KDM6A tumours." (PMID 34006303, 2021). "In recent years, KDM6A is found to be aberrantly expressed in many cancers as a tumor suppressor or promoter, implying its regulatory role in tumor initiation and progression." (PMID 34950587, 2021). "A subcutaneous tumour model and tail vein tumour injection in nude mice were used to assess the role of KDM6A in vivo." (PMID 34006303, 2021). "Loss of KDM6A results in malfunctioning of this complex, causing reduced H3K4 methylation leading to upregulation of oncogenic ETS and repression of tumor suppressive GATA transcriptional programs." (PMID 34944554, 2021). "One study has shown that six of such genes show increased loss-of-function mutations in male tumor diseases (ATRX, CNKSR2, DDX3X, KDM5C, KDM6A, and MAGEC3)." (PMID 32629877, 2020). "We further provide epigenomic, biochemical, and genetic evidence that mechanistically link HNF1A function in pancreatic exocrine cells to KDM6A, an established tumor suppressor." (PMID 32154941, 2020). "The KMT2C(MLL3)-KDM6A(UTX)-PRC2 regulatory axis modulates the expression of various downstream tumour suppressor genes, and thus the inactivation of KDM6A results in the activation of super-enhancers and contributes to the squamous subtype of PDAC in females." (PMID 33008426, 2020). "KDM6A in particular has been found to contribute to sex differences in bladder cancer, where it acts as a tumor suppressor in XX individuals." (PMID 32295632, 2020).
tumor (continued). "Transplantation of relapsed tumor cells from this patient into immunodeficient mice (PDX model) resulted in stable regeneration of KDM6A E1325X mutant clone (PDX AML-393), which was verified by Sanger sequencing." (PMID 31201358, 2020). "To further elucidate the mechanism of ENT1 regulation by KDM6A, we performed ChIP-seq analysis for H3K27me3 and H3K27ac in MM-1 and MM-6 cells as recent studies have reported that the tumor suppressor effect is largely demethylase independent." (PMID 31201358, 2020). "KDM6A was initially characterized as a tumor-suppressor, which can repress Notch and Rb-induced tumors in Drosophila." (PMID 33003334, 2020). "Our data suggest that EZH2 inhibition in the context of KDM6A and/or SWI/SNF mutations increase NK cell activity that mediates IFN-γ release to cause tumor cell death." (PMID 30692641, 2019). "In muscle-invasive bladder cancer (MIBC), KDM6A and members of the SWI/SNF family members are frequently mutated, while EZH2 is overexpressed in tumors compared to adjacent non-tumor areas." (PMID 30692641, 2019). "KDM6A catalyses the demethylation of H3K27me2 and H3K27me3, and a mutation in KDM6A is therefore to lead to an increase in H3K27 methylation, which is functionally equivalent to the enhanced EZH2 activity found in different human tumours." (PMID 30344952, 2018). "Overall, 22.6% of tumours harboured a coding mutation in one of the seven Mut-driver genes involved in chromatin function (KMT2C, ARID1A, NCOR1, CTCF, KDM6A, PRBM1 and TBL1XR1)." (PMID 27161491, 2016). "While some of the mutations are oncogenic (i.e., IDH1/2, EZH2, and DNMT3A), others are tumor suppressive (i.e., KDM6A, CREBBP/EP300, and SMARCB1)." (PMID 27999365, 2016). "In tumors three and four, there was a distinct somatic mutation in MTOR (categories 2 and 3, respectively) in each tumor, and PBRM1 and KDM6A and NRAS mutations (all category 3) in tumor three." (PMID 25159823, 2014). "Interestingly, we found that KDM6A KO (#1 and #2) showed a delay in tumor growth compared with control and parental-derived tumors." (PMID 41085408, 2025). "Loss-of-function mutations in the Lysine Demethylase 6A (KDM6A), Lysine Methyltransferase 2C (KMT2C), and Zinc Finger MYM-Type Containing 3 (ZMYM3) are enriched in Group 4 tumors, indicating convergent epigenomic dysregulation in tumor development." (PMID 40867227, 2025). "Furthermore, KDM6A-depleted fibroblasts significantly increased tumor formation in xenografted HCT116 cells from 50% (6/12) to 100% (12/12)." (PMID 40659611, 2025). "Furthermore, CREB knockdown led to increased sensitivity to cisplatin with reduced levels of TNKS and KDM6A in both cisplatin-resistant tumor spheroids and tumors in a xenograft mouse model." (PMID 40860181, 2025). "UTX (also known as KDM6A) is a histone H3K27 demethylase that acts as an important tumor regulator." (PMID 40536321, 2025). "KDM6A, a tumor suppressor gene, influences cancer cell growth." (PMID 40693457, 2025). "Additionally, KDM6A overexpression enhances chemoresistance in NSCLC stem cells and is associated with increased tumor recurrence following cisplatin treatment." (PMID 40860181, 2025). "The protein levels of TNKS and KDM6A were upregulated in tumor tissues compared to those in adjacent normal tissues, suggesting that these proteins could be promising targets for cancer treatment." (PMID 40860181, 2025). "KDM6A is one of the genes covered by the targeted tumor-sequencing test, such as MSK-IMPACT, indicating that KDM6A mutation may be easily analyzed." (PMID 39941725, 2025). "Furthermore, we observed that the dead mutant rescued the tumorigenic phenotype similar to KDM6A WT, decreasing the median survival of KDM6A KO from day 57 to day 39 for both conditions, whereas tumor growth was partially recovered." (PMID 41085408, 2025). "Another finding of this study is the role of KDM6A in tumor metabolism." (PMID 38840262, 2024).
tumor (continued). "The catalytic inactivation induced by mutation in JmjC or TPR domain can also abolish the tumor suppressive function of KDM6A, suggesting that KDM6A suppresses tumorigenesis independent of its histone demethylase capability." (PMID 38850159, 2024). "In B cell cancers, it has been identified as a tumor suppressor and, in recent studies, B cell activation, isotype switching, and plasma cell differentiation were restrained by KDM6a activity, suggesting different functional roles in different lymphocyte populations." (PMID 38486287, 2024). "For instance, high tumor incidence is observed in KDM6A knockout mouse." (PMID 38850159, 2024). "However, our study provides an alternative approach for targeting MMP3 via KDM6A inhibition to prevent brain metastases of KMT2C or KMT2D mutant tumours." (PMID 38926506, 2024). "Additionally, intrinsic disorder sequence between TPR and JmjC domains regulates the distribution of KDM6A on chromatin through phase separation and play an important role in tumor suppression." (PMID 38850159, 2024). "Furthermore, the tumor tissues with KDM6A knocked-out expression exhibited elevated Ki67 expression, as evidenced by Ki67 staining." (PMID 38840262, 2024). "However, the authors of this study also found an upregulated mRNA level of KDM6A in HCC tumour tissues, which was consistent with our results." (PMID 37846441, 2023). "Moreover, KDM6A plays a vital role in the tumour progression of various cancer types such as colorectal cancer, breast cancer and bladder cancer and serves as a tumour suppressor or oncogene, depending on the cancer types." (PMID 37846441, 2023). "Furthermore, sustained suppression by two validated Kdm6a short hairpin RNAs (shRNAs) also cooperated with Myc to produce HCCs on HDTVi, providing further validation of the tumour suppressive action of Kdm6a using an orthogonal approach." (PMID 34509979, 2022). "Next, we asked if sustained Kdm6a suppression is important for tumour maintenance." (PMID 34509979, 2022). "Interestingly, we found in genetic epistasis experiments that Kdm6a-dependent tumour suppression was largely Deptor dependent, indicating that Deptor is one of the main Kdm6a targets mediating its tumour suppressive abilities." (PMID 34509979, 2022). "Similarly, the loss of KDM6A copy number was also detected in all samples, despite KDM6A’s diverse expression and methylation status within and across individual tumours from P8 to P19." (PMID 35061935, 2022). "Consequently, Kdm6a protein levels were undetectable in on-Dox tumours, but strong nuclear expression of Kdm6a was visible in off-Dox tumours." (PMID 34509979, 2022). "Moreover, in vitro and in vivo genetic epistasis experiments illustrated a crucial function of Deptor and mTORC1 in Kdm6a-dependent tumour suppression." (PMID 34509979, 2022). "Interestingly, KDM6A is located on the X-chromosome and was previously shown to escape X-inactivation, 27 thus being a putative monoallelic tumour suppressor exclusively in men." (PMID 34509979, 2022). "To determine whether disruption of Kdm6a in HSPCs only (mediated by Vav1-Cre) might lead to hematopoietic malignancies, we performed an 18-month tumor watch." (PMID 34780480, 2021). "Second, the molecular mechanism by which KDM6A might suppress tumour progression need further research." (PMID 34051747, 2021).
tumor (continued). "It included two established tumor suppressor escapees, in other words EXIT genes, previously suspected to be associated with excess cancer in men, namely KDM6A and DDX3X, both showing 25% higher expression in women (FC = 0.8; q = 1.7 × 10−38 and q = 1.5 × 10−15, respectively)." (PMID 33527138, 2021). "The finding that FOXA1 activates KDM6A transcription prompted us to investigate whether the KDM6A-ARHGDIB axis mediates the tumour-suppressive effect of FOXA1 in BCa cells." (PMID 34006303, 2021). "In addition to mutations of FGFR3 and KDM6A, we identify ZFP36L1 as a novel, significantly mutated tumor suppressor gene." (PMID 33397444, 2021). "This suggests KDM6A may operate in a cell type dependant manner and further investigation is required to resolve the tumor suppressive vs oncogenic role in different types of cancer." (PMID 34220955, 2021). "A significant difference in the performance of KDM6A in tumor and normal tissues were confirmed." (PMID 33174323, 2021). "Nevertheless, the molecular mechanism by which KDM6A might suppress tumour progression in BC remains unclear." (PMID 34051747, 2021). "KDM6A is initially a tumor-suppressor of Notch and Rb-dependent tumors in Drosophila." (PMID 34950587, 2021). "The KDM6A-ARHGDIB axis was further confirmed by IHC in the tumour xenograft models." (PMID 34006303, 2021). "The tumor mutation load showed BCL6 corepressor like 1 (BCORL1) and a-raf proto-oncogene (ARAF) have the highest copy number amplification, whereas lysine demethylase 6A (KDM6A) and RNA binding motif protein 10 (RBM10) showed the highest copy number deletion." (PMID 33629637, 2021). "KDM6A was suggested to act as a tumour suppressor in several cancers." (PMID 34051747, 2021). "Furthermore, in an oncogenic KrasG12D-induced lung cancer mouse, deletion of KDM6A gene accelerated disease progression and increased tumour burden." (PMID 34572020, 2021). "KDM6A, a known tumor suppressor, is frequently inactivated in cancers." (PMID 34950587, 2021). "Dependent on the cancer type, KDM6A appears to possess distinct tumor-suppressive functions." (PMID 31201358, 2020). "Of note, truncating mutations in KDM6A, KMT2D, and KMT2C were frequently observed (74%; 14/19), suggesting that disruption of the epigenetic regulatory pathway may be involved in tumor development in urothelial BC." (PMID 32984035, 2020). "The analysis also confirmed a partial correlation of KDM6A with immune tumor infiltrates." (PMID 32731355, 2020). "This suggested that Kdm6a could exert its tumor suppressor function through broadly similar pathways as Hnf1a, namely through the maintenance of acinar differentiated cell programs and inhibition of growth‐promoting pathways." (PMID 32154941, 2020). "In addition, KDM6A/KDM6B knockdown or upregulation of H3K27me3 levels sensitized OS to cisplatin by enhancing apoptosis in tumor cells." (PMID 30651137, 2019). "Although we have provided evidence that mechanisms can be shared between different malignancies, it remains to be determined whether BAP1 and KDM6A alterations are promoting tumour growth in SPNs through a similar epigenetic mechanism." (PMID 30306561, 2019). "Collectively, our results indicated that KDM6A or KDM6B knockdown could sensitize OS to cisplatin by enhancing apoptosis of tumor cells." (PMID 30651137, 2019). "Kdm6a (Utx) has been identified as a candidate tumor suppressor in cancer genetics studies." (PMID 30963999, 2019). "While many studies demonstrate the mutations of KDM6A and KDM6B in cancers and suggest a tumor-suppressive function of these two demethylases, several studies show KDM6A and KDM6B may exhibit oncogenic activity." (PMID 28717873, 2018). "In patient 4 (5 intra-tumor pieces), PBRM and KDM6A genes were mutated only in tumor piece 1 and 4 respectively but not in any of the other five tumor pieces." (PMID 29187174, 2017).
tumor (continued). "Similarly, investigations into the role of inactivating mutations in chromatin modifiers (i.e. KDM6A, CREBBP/EP300, SMARCB1) implicate many of these genes as tumor suppressors." (PMID 24622842, 2014). "Candidate epigenetic driver genes have been identified as either mutated across many cancers (e.g. KDM6A in over 12 cancers), having highly recurrent mutations (e.g. IDH1 R132), or having highly prevalent mutations in select tumor histologies (e.g. MLL2 in follicular lymphoma)." (PMID 24622842, 2014). "In addition to contributing to tumor suppression via its catalytic domain, KDM6A also has important demethylase-independent roles in cancer." (PMID 24622842, 2014). "Therefore it will be important to determine the mechanisms of E7 mediated KDM6A induction, the transcriptional consequences of KDM6A expression and the mechanisms by which E7 subverts KDM6A tumor suppressor activity." (PMID 23673719, 2013). "Lysine demethylase 6A (KDM6A), a H3K27 demethylase and key component of the COMPASS complex, is frequently mutated in hematologic malignancies, but its roles in embryonic hematopoiesis and tumor suppression in CMML remain unclear." (PMID 40365824, 2025). "Notably, even catalytically inactive KDM6A mutants partially suppress tumor cell proliferation." (PMID 41019050, 2025). "Targeting KDM6A could inhibit JIMT1 tumor growth via decreasing tRNA transcription." (PMID 40464376, 2025). "Thus, we speculate that KDM6A play a pivotal role in maintaining genomic stability and preventing tumorigenesis and tumor progression." (PMID 38850159, 2024). "The main body of data indicates that the KDM6A/UTX demethylase protein acts as a tumour suppressor, and that tumours lacking or carrying mutations in KDM6A may, in some cancers, be targeted with either EZH2 or BET inhibitors." (PMID 35406676, 2022). "In addition, higher expression of ATRX, DDX3X, KDM5C and KDM6A was observed in female patients, indicating that tumor-suppressor genes that escape from X-inactivation may contribute to HCC sex bias." (PMID 36118521, 2022). "In addition, a group of tumor suppressors that escape from X-inactivation have been implicated in cancer sex bias 30, our analysis did reveal higher expression of ATRX, DDX3X, KDM5C and KDM6A in female than male patients." (PMID 36118521, 2022). "Thus, Deptor and mTORC1 signalling are crucial determinants for Kdm6a-dependent tumour suppression." (PMID 34509979, 2022). "Furthermore, low tumor KDM6A expression was associated with higher UBC tumor stage in women, but not in men." (PMID 34768683, 2021). "Hence, we evaluated the KDM6A expression of different MMR status in tumor tissues." (PMID 33174323, 2021). "Thus, inactivation of one KDM6A allele in males contributes to tumor development, while in females, it does not, because cells still express the second wild type allele." (PMID 34440292, 2021). "We observed reduced infiltration of immune cells in KDM6A-mutated tissues, including neutrophils, macrophages, and CD8+ T cells, which is consistent with previous reports showing that these immune cells play key roles in the tumour microenvironment and suppress the immune response." (PMID 34051747, 2021). "Moreover, the downregulation of KDM6A was shown to correlate tightly with the progression to advanced stages, and both the reduced mRNA levels and mutations of KDM6A predicted the poor outcome in BCa patients, suggesting the tumour-suppressive role of KDM6A in BCa." (PMID 34006303, 2021). "Although mechanisms are not always shared among tumour types, we sought to investigate whether mutation or reduced expression of KDM6A was also associated with a hypoxic signature in SPNs." (PMID 30306561, 2019). "Interestingly, a paternal age effect has been reported for ALL, a tumor shown to be sensitive to epigenetic regulation by KDM6A, but increased rates of inherited de novo mutations have not yet been demonstrated for ALL patients." (PMID 30963999, 2019).